EFR3B (EFR3 homolog B)
Description:
Component of a complex required to localize phosphatidylinositol 4-kinase (PI4K) to the plasma membrane. The complex acts as a regulator of phosphatidylinositol 4-phosphate (PtdIns(4)P) synthesis (Probable). In the complex, EFR3B probably acts as the membrane-anchoring component. Also involved in responsiveness to G protein-coupled receptors; it is however unclear whether this role is direct or indirect.
Synonyms: KIAA0953; FLJ37871
Tractability: Antibody: UniProt places it where antibodies can reach, with high confidence; its Gene Ontology location is reachable by antibodies, with high confidence; the Human Protein Atlas places it where antibodies can reach. PROTAC: ubiquitination databases record sites on it; its protein half-life has been measured.
Gene: Protein-coding gene on chromosome 2 (25,042,048 to 25,159,135, forward strand). Ensembl gene ENSG00000084710.
Subcellular location: Cell membrane; Cytoplasm, cytosol
Subcellular location (Human Protein Atlas): Plasma membrane; Actin filaments; Cytosol
Gene Ontology:
Molecular function: protein binding
Biological process: phosphatidylinositol phosphate biosynthetic process; protein localization to plasma membrane
Cellular component: cytosol; plasma membrane
Genetic constraint (gnomAD): Loss-of-function variants: 63 observed, 103.96 expected, observed/expected ratio (o/e) 0.61, 90% interval 0.49 to 0.75. The upper end of that interval is the gene's LOEUF score, 0.75, which puts it in group 3 of 6, group 1 being the genes least tolerant of losing a copy. Missense variants: 742 observed, 1,102.4 expected, observed/expected ratio (o/e) 0.67, 90% interval 0.63 to 0.71. Synonymous variants: 377 observed, 425.85 expected, observed/expected ratio (o/e) 0.89, 90% interval 0.81 to 0.96.
Homologues: Orthologues: macaque EFR3B (100% identical), chimpanzee EFR3B (99% identical), pig EFR3B (98% identical), rat Efr3b (98% identical), guinea pig EFR3B (98% identical), mouse Efr3b (98% identical), tropical clawed frog efr3b (87% identical), dog EFR3B (86% identical), zebrafish efr3bb (80% identical), zebrafish efr3ba (77% identical), rabbit EFR3B (75% identical), Drosophila melanogaster stmA (41% identical), and 1 more. Paralogues in human: EFR3A (63% identical).
Diseases named in the same sentence as EFR3B in open-access papers:
EFR3B is named in the same sentence as 10 diseases in open-access papers, as found by Europe PMC text mining. Sharing a sentence is not in itself a finding about the gene and the disease. The quoted sentences say what the papers report.
Obesity (3 papers, 2021 to 2024). Accumulation of substantial excess body fat. "Among these obesity-associated genes, three genes (NUGGC, EFR3B, and SOX4) were found to be upregulated or downregulated according to the presence of obesity both in the literature and in the current study." (PMID 34381138, 2021).
pancreatic cancer (2 papers, 2021 to 2025). "Human EFR3A and EFR3B also regulate KRAS signalling at the plasma membrane in pancreatic cancer cells." (PMID 39991135, 2025).
diabetes (1 paper, 2014). "Ontological classification demonstrates that these 14 genes are associated with diabetes (ALMS1P; RAET1L; GYS1; RBM47; EFR3B), cancer (RPL27A; SPAM1; PTCH1; ZNF277; USP35; CDC86), or metabolism (C3orf15; AOC2; GOT1)." (PMID 24885560, 2014).
glioblastoma (1 paper, 2025). The most malignant astrocytic tumor (WHO grade IV). "In vitro, validation experiments performed on glioblastoma cell line GSC-0827 expressing high levels of EFR3B (EFR3Bhigh) and glioblastoma GSC-0131 cell line with trace expression of EFR3B (EFR3Blow) confirmed the compensatory relationship between EFR3A and EFR3B." (PMID 40305161, 2025).
pancreatic adenocarcinoma (1 paper, 2021). "In sum, loss of EFR3A (and/or EFR3B) expression inhibits oncogenic signaling in human KRAS-mutant pancreatic adenocarcinoma cells, which manifests as a reduction in transformed and tumorigenic growth." (PMID 34504076, 2021). "As above, we validated these results in 3D-transformed growth, again finding that loss of EFR3A, EFR3B, or both reduced colony formation of all four pancreatic adenocarcinoma cells in soft agar." (PMID 34504076, 2021). "Furthermore, loss of EFR3A, EFR3B, or both reduced tumor growth of a human pancreatic adenocarcinoma cell line in vivo." (PMID 34504076, 2021). "To evaluate the role of endogenous EFR3A in a cancer driven by an oncogenic mutation in the native KRAS gene, we targeted EFR3A, EFR3B, or both genes by CRISPR/Cas9-mediated gene inactivation as above in the KRAS-mutant human pancreatic adenocarcinoma cell line HPAF-II47." (PMID 34504076, 2021).
type 1 diabetes (1 paper, 2024). "The EFR3B gene is considered a candidate gene for human type 1 diabetes." (PMID 38674346, 2024).
tumor (2 papers, 2019 to 2021). "CELF2 is a tumor suppressor, and EFR3B contributes to the control of the phosphorylation state and could affect the responsiveness of G-protein-coupled receptors in higher eukaryotes." (PMID 31379917, 2019). "We show that this reduction in tumor growth was, as in 2D- and 3D-transformed growth assays, associated with a reduction in oncogenic KRAS signaling, namely we observed a reduction in P-ERK and P-AKT levels in tumors in which EFR3A, EFR3B, or both genes were inactivated." (PMID 34504076, 2021).
EFR3B also shares sentences with these, for which no sentence is quoted: cancer (3 papers); glioma (1); osteoporosis (1).